CD4 (CD4 molecule)
Diseases named in the same sentence as CD4 in open-access papers (continued):
Sharing a sentence is not in itself a finding about the gene and the disease.
myocarditis (168 papers, 2010 to 2025). Myocarditis is a condition that is characterized by inflammation of the heart muscle (myocardium). "In the early case report of ICI-associated myocarditis, histological analysis in humans confirmed infiltration of T lymphocytes (both CD4 and CD8 cells) and macrophages, suggesting immune infiltration as the main pathophysiological driver." (PMID 40165308, 2025). "Inhibition of PGK1 by NG52 reduced the cardiac damage caused by myocarditis and altered the infiltration patterns of CD4+ T cells, including Th17 cells, Th1 cells, and Tregs." (PMID 40356915, 2025). "Early histopathological examination of ICI-associated myocarditis demonstrated abundant infiltration of CD4+ and CD8+ T cell in myocardium, cardiac conduction system, and skeletal muscle." (PMID 40740863, 2025). "Histologically, ICI-associated myocarditis is associated with infiltration of CD4+ and CD8+ T cells and CD68+ macrophages into the myocardium and conduction system." (PMID 40547024, 2025). "In autoimmune-prone mice (Murphy Roths Large, MRL), loss of PD-1 resulted in spontaneous myocarditis with an increased number of central memory CD4+, Treg, and effector memory CD8+ T cells in the myocardium." (PMID 39023770, 2025). "Transferring the splenocytes and purified CD4+ T cells into T cell-deficient BALB/c athymic nude mice led to myocarditis, indicating that this condition is T cell-mediated." (PMID 39039301, 2025). "Johnson and colleagues' report indicates that the myocarditis linked with ICIs involves the infiltration of CD4+ and CD8+ T cells, along with CD68+ macrophages, into the myocardium and conduction system." (PMID 38169638, 2024). "From a histological perspective, myocarditis associated with ICIs is distinguished by the infiltration of CD4+/CD8+ T cells, CD68+ macrophages, and a decrease in other immune cell populations within the myocardium." (PMID 38482205, 2024). "HHV6-induced myocarditis has been associated with a myocardial infiltration of CD4+ and CD8+ T cells." (PMID 38464847, 2024). "The histopathological characteristics of ICI-associated myocarditis involve infiltration of T lymphocytes (both CD4+ and CD8+), macrophages, and myocyte death, whereas B lymphocytes are not observed." (PMID 37876928, 2023). "Pathologically, ICI-associated myocarditis is associated with the infiltration of CD4+/CD8+ T cells, CD68+ macrophages, and a paucity of other immune cells in the myocardium." (PMID 36354777, 2022). "PD-L1 expression is higher in cardiac tissue samples from patients with ICI-associated myocarditis, which is consistent with lymphocytic myocarditis as histologically characterized by myocardial infiltration of macrophages and CD4+/CD8+ T lymphocytes." (PMID 36185227, 2022). "Myocardial features identified on EMB for ICI-associated myocarditis include interstitial fibrosis, lymphocyte infiltration, T cells (CD4+, CD8+), macrophage infiltration, and other inflammatory changes." (PMID 36185227, 2022). "CD4+ T cells are key pathogenic players underlying the development and progression of myocarditis, and the effector subsets promote autoimmune responses." (PMID 33466825, 2021). "CD4+ T cells are key pathogenic factors underlying the development and progression of myocarditis, and the effector and regulatory subsets, respectively, promote and inhibit autoimmune responses." (PMID 32269577, 2020). "A recent study proposed that VMC pathology is driven by IL-17-producing CD4+ T cells because the severity of myocarditis in T-bet-knockout mice was associated with increased IL-17 expression in the heart." (PMID 33817288, 2020). "Our data underline potential importance of antigen-independent CD4+ T cell responses in the progression from myocarditis to DCM and attribute them a cardioprotective role." (PMID 31863205, 2019). "CD4+ T cells and particularly the Th17 subset have been implicated in transition from myocarditis to DCM phenotype." (PMID 31863205, 2019).
myocarditis (continued). "Heart-specific CD4+ T cells have been implicated in development and progression of myocarditis in mice and in humans." (PMID 31863205, 2019). "Histological analyses of patients and monkey models with ICI-associated myocarditis have revealed that the infiltration of predominant CD4+/CD8+ T lymphocytes and a few macrophages (CD68+ cells) are the main cause of ICI-associated myocarditis." (PMID 31849640, 2019). "Myocarditis, which involves inflammatory CD4+ and CD8+ T cells and macrophages, is associated with severe Chagas heart disease." (PMID 29696014, 2018). "These cells are directly pathogenic, because adoptive transfer of heart-specific CD4+ T cells can induce myocarditis in irradiated recipients, SCID, or Rag2−/− mice." (PMID 30035131, 2018). "Adoptive transfer of CD4+ T cells depleted from highly efficient glucocorticoid-induced TNFR family-related gene/protein-expressing Treg resulted in more severe myocarditis in T cell-deficient BALB/c nude mice." (PMID 30035131, 2018). "HIV-associated cardiac involvement presenting as myocarditis, left ventricular dysfunction, and dilated cardiomoypathy has been described in patients with advanced disease with low CD4 counts such as the majority of the children in our cohort." (PMID 20482796, 2010). "Furthermore, multiple previous studies have linked activated effector CD4+ T-cells to fatal myocarditis." (PMID 38236243, 2024). "CD4+ T cells are key pathogenic factors in the development and progression of myocarditis." (PMID 38741130, 2024). "However, there is no consensus for which IHC stains should be performed in cases of suspected ICI-associated myocarditis and several studies have reported a wide array of IHC staining including CD4, CD8, CD3, CD68, CD20, PD-1, and PD-L1." (PMID 36915213, 2023). "Furthermore, dysregulated autoreactive CD4+ T cells and their cytokines are critical for the autoimmune-related induction of myocarditis in genetically predisposed individuals." (PMID 36005648, 2022). "Murine models shed light on mechanistic processes in which CD4+ T cells may regulate or promote myocarditis, but whether the CD4+ T cell accumulation in myocardium is a cause or a consequence of progressive cardiomyopathy, is still under investigation." (PMID 36447264, 2022). "However, in mice, the myocarditis was caused by CD4+ and CD8+ T cells as well as autoantibodies against cardiomyocytes." (PMID 34680365, 2021). "In addition, PD-1 deficient mice were more likely to be infected with autoimmune myocarditis than control mice by immunizing CD4+ T cells induced by cardiac myosin, which can cause myocarditis." (PMID 33643048, 2021). "Using the haploinsufficient mice, we addressed whether ROCK1 or ROCK2 was implicated in the development of CD4+ T cell-mediated myocarditis." (PMID 32178482, 2020). "However, these chronically T. cruzi-infected CCR5-deficient mice presented more intense myocarditis with macrophages, CD4+ and CD8+ cells." (PMID 29696014, 2018). "In contrast to autoantibodies, CD4 T cell clones isolated from myocarditis heart lesions of DQ8+NOD mice predominantly recognized α-MyHC and adoptively transferred disease into immunodeficient hosts, demonstrating that α-MyHC-reactive CD4 T cells cause myocarditis [13••]." (PMID 25821130, 2015). "Additionally, emerging evidence from preliminary mechanistic studies suggested that central memory CD4+ T cells may play a protective role in ICI-associated myocarditis." (PMID 40740863, 2025). "Moreover, the development of myocarditis in patients with cancer treated with immune checkpoint inhibitors underscores the severe immunopathological damage caused by unleashing both CD4+ and CD8+ T cell reactivity against self-antigens in the cardiac microenvironment." (PMID 39196111, 2024). "Furthermore, long-term activation of Treg cells could lead to the loss of CD4+ T cell immune function and promote myocarditis." (PMID 32269577, 2020).
myocarditis (continued). "The HIPPO signaling pathway is significantly activated in heart CD4+ T cells in ICI-related myocarditis." (PMID 40356915, 2025). "Nevertheless, recently central memory CD4+ T cells have also been shown to have a protective role against ICI myocarditis." (PMID 39023770, 2025). "In agreement with our histopathological finding of myocarditis, we found that most intracardiac immune cell populations were elevated, especially CD4+ and CD8+ T cells, macrophages, and NK cells." (PMID 39791886, 2025). "For example, CD4+ T cells are required for the development of myocarditis in CVB3-infected and EAM mice, and Th17 cells promote progression of ICM to DCM." (PMID 40092999, 2025). "Ultimately, NG52 inhibited the responses of CD4+ T cells and Th17 cells from patients with myocarditis." (PMID 40356915, 2025). "Analysis utilizing the CIBERSORT algorithm on five pediatric patients with myocarditis revealed that activated NK cells were predominant in two patients, while activated memory CD4+ T cells and M2 macrophages each predominated in one patient." (PMID 40230577, 2025). "Further, in mice with coxsackievirus B3 (CVB3)-induced myocarditis, CD4+ T cells are critical for disease, whereas CD8+ T cells can attenuate disease." (PMID 40092999, 2025). "α–Myosin heavy chain (α-MyHC), a component of the thick filament in myocytes, was used as a primary autoantigen for CD4+ T cells in a spontaneous mouse model of myocarditis." (PMID 39817455, 2025). "Experimental autoimmune myocarditis (EAM) serves as an animal model of CD4+ T cells-dependent acute myocarditis that is followed by the development of post-inflammatory DCM." (PMID 41341993, 2025). "One of the many examples that we have shown in our results is the finding that CD4+ T cells are more responsive compared to CD8+ T cells during myocarditis." (PMID 41332779, 2025). "The study found that molecular imaging with targeted microbubbles provided increased signal detection in moderate and severe myocarditis, correlating with CD4+ T-cell infiltration in the myocardium." (PMID 40948965, 2025). "Experiments employing knockout mice and adoptive transfer approaches have additionally substantiated the indispensable contribution of CD4 + T cells in the progression of myocarditis, mirroring the characteristics observed in human myocarditis." (PMID 39075540, 2024). "XMU-MP-1 weakened the therapeutic effect of LIPUS, and myocardial inflammation in mice was better than that in the PD-1 inhibitor group; therefore, activation of the HIPPO pathway in CD4+ T-cells contributes to LIPUS for improving ICI-related myocarditis." (PMID 38236243, 2024). "In a similar vein, the absence of PD-1 has been found to worsen cardiac damage in models involving CD8+ and CD4+ T cell-mediated myocarditis." (PMID 38482205, 2024). "Severe combined immunodeficient mice developed myocarditis dominated by CD4+ T cells, while depletion of CD4+ T cells suppresses the inflammation." (PMID 38464847, 2024). "In a T cell receptor (TCR) transgenic mouse model specific for myosin heavy chain α (residue 614–629) spontaneously developing myocarditis, heart-infiltrating CD4+ T cells secrete IFN-γ and IL-17, indicating their Th1/Th17 phenotype." (PMID 39768171, 2024). "We also present evidence that the cytotoxic functions of CD4+ and CD8+ T cells expressing Myhc-α 334–352-specific TCRs are comparable in the causation of myocarditis in these mice." (PMID 38334626, 2024). "The effector CD4+ T cells exacerbate myocarditis by promoting viral replication, secretion of cytokines, myeloid cell infiltration, and myocardial fibrosis." (PMID 38741130, 2024). "In mice with myocarditis induced through the transfer of CD4+ T cells, Th1 and Th17 cells were found to infiltrate the myocardium." (PMID 38464847, 2024). "The beneficial effects of acacetin on myocarditis are mainly related to inhibiting CD4+ T cell activation, proliferation and Th17 cell differentiation." (PMID 38741130, 2024).
myocarditis (continued). "The present study revealed that acacetin inhibited the development of myocarditis by suppressing CD4+ T cell activation and Th17 cell differentiation in vivo and in ex-vivo, which is consistent with previous reports." (PMID 38741130, 2024). "The patients were diagnosed with myocarditis with scattered lymphocyte infiltration, especially for CD4 + cells in the myocardium." (PMID 39075540, 2024). "A multitude of investigations, predominantly carried out in murine models, have underscored the crucial involvement of CD4 + T cells in the pathogenesis and advancement of myocarditis." (PMID 39075540, 2024). "Transgenic mice expressing a targeted CD4 + T cell receptor for cardiac myosin exhibit spontaneous myocarditis, which subsequently evolves into fatal dilated cardiomyopathy." (PMID 39075540, 2024). "In further studies, it should focus on the fine-tuning mechanism and interaction of bystander-activated CD4+T cells in the development of ICI-related myocarditis." (PMID 38236243, 2024). "The present study aimed to explore the autoimmune response during LIPUS treatment of ICI-related myocarditis, which is primarily mediated by CD4+ T-cells; thus, CD4+ T cells were selected for the present analyzes." (PMID 38236243, 2024). "Myocarditis with the presence of mainly mononuclear cells, CD4 T lymphocytes, CD8 T lymphocytes, and macrophages in mice with chronic infection had been observed." (PMID 38576607, 2024). "The concurrent deletion of both CD4 + and CD8 + T cells exhibited the most notable protective effects, underscoring the significance of CD4 + helper T cells in the pathogenesis of myocarditis." (PMID 39075540, 2024). "A mouse model of ICI-related myocarditis mimicked the pathogenesis of myocarditis, with peak cardiac inflammation occurring between 14 and 21 d, and was characterized by the infiltration of heart-specific CD4+ T-cells into the myocardium." (PMID 38236243, 2024). "In the study, it was observed that four out of five patients with myocarditis displayed an imbalance between Th1 and Th2 immune cells, which resulted in significant inflammatory responses from Th1, Th1/Th17, and Th17 CD4 memory T-cells." (PMID 38169638, 2024). "Myocarditis refers to an autoimmune inflammatory response of the myocardium with characterization of self-reactive CD4+ T cell activation, which lacks effective treatment and has a poor prognosis." (PMID 38741130, 2024). "The biopsy results confirmed the presence of acute myocarditis, characterized by a predominance of CD4+ T-lymphocytes, a hallmark feature of ICI-associated myocarditis." (PMID 39279887, 2024). "The HIPPO signaling pathway was significantly activated in cardiac CD4+ T-cells in ICI-related myocarditis." (PMID 38236243, 2024). "We identified important associations between these myocarditis-like MRI abnormalities and altered immune responses, including increased cytotoxic CD8 T cells, CD4 Th2 cells, TNF-α producing monocytes, and several key inflammatory mediators." (PMID 39073768, 2024). "In an analogous model of experimental myocarditis, exogenously stimulated DCs expressing α-Myosin peptide also stimulated CD4+ and CD8+ cellular infiltrations in myocardial tissue in mice." (PMID 37892217, 2023). "AC-73 inhibited T cell activation and T cell recruitment to the heart instead of affecting the differentiation of splenic CD4+ T cell subsets in our CVB3-induced myocarditis model." (PMID 37243223, 2023). "Data from C57BL/6 mouse models show that acute CVB3-induced myocarditis is characterized by inflammatory infiltration of immune cells, including CD4+ and CD8+ T cells." (PMID 38274806, 2023). "They found that myocarditis severity in the CD4 knockout group, CD4 and CD8 knockout group, and TCR beta knockout group was lighter than that in the CD8 knockout group." (PMID 37260696, 2023). "Acute CVB3-induced myocarditis is characterized by inflammatory infiltration of immune cells, including CD4+ and CD8+ T cells." (PMID 37669302, 2023).
myocarditis (continued). "CD4+ regulatory T cells (Tregs) have been found to reduce the intensity of acute cardiac inflammation and restrain the development of myocarditis into dilated cardiomyopathy." (PMID 37512058, 2023). "For example: MYH6 is suggested to be targeted on CD4+ T cell in a spontaneous mouse model of myocarditis." (PMID 37691828, 2023). "Differences in the Th1 and Th2 CD4+ T cell responses between males and females influence myocarditis in mice." (PMID 37669302, 2023). "In this model, differences in the CD4+ T helper (Th) 1 and Th2 response following infection contribute to the sex bias in myocarditis." (PMID 38274806, 2023). "In myocarditis, CD4+ T cells are known to be essential effector cells; on the other hand, Th17 cells increase pro‐inflammatory factor release and promote disease progression." (PMID 37382257, 2023). "The crucial role of self-reactive CD4+ T cells in myocarditis induction is well described, although the mechanisms still remain poorly understood." (PMID 37627502, 2023). "It has been reported that the mRNA-1273 vaccine can induce a strong CD4 cytokine response involving type 1 helper T (Th1) cells, and CD4 cells are an important factor in myocarditis." (PMID 35369340, 2022). "CD4+ IL-17+ cells have been found to be increased in peripheral blood from acute myocarditis patients but also in patients with melanoma under ICI treatment." (PMID 36139654, 2022). "In acute myocarditis, a shift of CD4-to-CD8 ratio towards CD8+ T cells is known, explaining the elevated CD8+ cells in AMC and GCMC patients." (PMID 35805941, 2022). "A correlation between the frequency of PRF+CD4+ T cells and two echocardiographic parameters employed for evaluating myocarditis in CC patients was also encountered." (PMID 35670567, 2022). "EAM is a CD4+ T cell-dependent myocarditis model consisting of the injection of an immunogenic fragment of the α-myosin heavy chain peptide (MyHCα 614–629) emulsified with complete Freund adjuvant." (PMID 36139654, 2022). "In animal models, sST2 has been found to be released predominantly from CD11b+ and CD4+ immune cells, which are the primary cardiac immune cells observed during acute myocarditis in mice and humans." (PMID 36741845, 2022). "Myocarditis lesions were composed of mainly T cells, with more CD4+ than CD8+ T cells, and macrophages." (PMID 36139654, 2022). "This is supported by histological data from ICI-induced myocarditis patients showing increased CD4 and CD8 lymphocytes and, to a lesser degree, macrophages." (PMID 35455289, 2022). "As a result, they suffer fulminant myocarditis with massive cardiac infiltration of CD4+ and CD8+ T cells and myeloid cells." (PMID 36139654, 2022). "A case of chronic smoldering myocarditis was diagnosed when the EBM revealed myocardial infiltration by CD4+ and CD8+ T lymphocytes together with a considerable number of histiocytes and macrophages." (PMID 36142866, 2022). "Typical findings of ICI-related myocarditis include lymphocyte (CD4+, CD8+) and macrophage infiltration and interstitial fibrosis in the affected area." (PMID 36358830, 2022). "Specific contribution of CD8+ and CD4+ T cells in ICI-myocarditis have also been studied in Pdcd1−/− mice." (PMID 36139654, 2022). "Staining for CD4 was detected in low levels in the inflammatory infiltrate of the hearts of any group with myocarditis." (PMID 34504808, 2021). "In CDR with central nervous system (CNS) involvement, a higher percentage of deaths, and lower level of CD4+ cells/μL at the reactivation time were registered over myocarditis and “others” presentations." (PMID 34591866, 2021). "In this study, we investigated the effects of cervical vagotomy and the α7nAChR agonist pnu282987 on CD4+ T cell differentiation in a murine myocarditis model (BALB/c) infected with coxsackievirus B3 (CVB3)." (PMID 33380272, 2021). "Some studies have reported inflammatory responses are significantly reduced in CD4 knockout mice with myocarditis." (PMID 33380272, 2021).